TNF (tumor necrosis factor)
Diseases named in the same sentence as TNF in open-access papers (continued):
Sharing a sentence is not in itself a finding about the gene and the disease.
asthma (continued). "In addition to previously identified variables, the data provide further evidence for the importance of IL-2, IL-5, IL-6, IL-8, IL-10, IFN-γ, TNF, asthma, polyposis, and aspirin sensitivity, in efforts to demarcate distinct endotypes of CRS." (PMID 30283438, 2018). "In addition, the application of the anti-TNF-α drugs that were aimed at the differential asthma phenotype and the right treatment prescription were significate in asthma therapy." (PMID 29751569, 2018). "Intriguingly, the relative abundance of nasal Moraxella was positively associated with systemic and airway eosinophil counts, suggesting associations with allergic inflammation, as well as with asthma-associated pro-inflammatory chemokine CXCL11 and TNF levels in bronchial lavage fluid." (PMID 29885665, 2018). "The treatment of infliximab could decrease the level of TNF-α and improve the lung function of moderate asthma patients and were well tolerated." (PMID 29751569, 2018). "ASMCs from patients with asthma are in a hyperproliferative phase, overexpress the chemokines chemokine (C–C motif) ligand (CCL) 11 (CCL11) and CXCL8, and particularly in patients with severe asthma, there is a reduced effect of corticosteroids in inhibiting TNFα-induced release of CCL11 and CXCL8." (PMID 28842514, 2017). "Third, because asthma is an inflammatory disease, TNF-α, a marker of inflammation may be elevated in youth with asthma as a result of the underlying disease and altered by controller medications, which have anti-inflammatory properties." (PMID 28609485, 2017). "Furthermore, excessive weight gain during pregnancy is a strong predictor for elevated levels of tumor necrosis factor α (TNF-α) in infants, and TNF-α has been associated with asthma by age 9 years." (PMID 29120703, 2017). "Verproside may be a good therapeutic candidate as an anti-asthma drug, blocking the tumor necrosis factor alpha (TNF-α)/nuclear factor kappa B (NF-κB) signaling pathway and reducing the levels of total immunoglobulin E, interleukin-4, and interleukin-13." (PMID 28441724, 2017). "Our study demonstrates that enhanced thrombin generation in asthma might be a reason of systemic inflammatory state and is, at least partially, driven by inflammatory cytokines, such as IL-6 and TNFα." (PMID 28429138, 2017). "In addition, identification of such profile provides illumination on the various biological mechanisms to the development of TNF-α high asthma." (PMID 28609485, 2017). "TNFα was higher in severe asthmatics as compared to mild-moderate asthma subjects and controls." (PMID 28429138, 2017). "Asthma was characterized by 62% higher plasma IL-6 and 35% higher TNFα (both, p < 0.0001)." (PMID 28429138, 2017). "This is consistent with our finding that pDC depletion produced significantly lower IL-6 and IFN-α, and somewhat lower TNF-α, consistent with the notion that pDC function might be impaired in asthma." (PMID 29118754, 2017). "Therefore, we investigated the associations between the previously analyzed parameters of a prothrombotic state in asthma and concentrations of IL-6 and TNFα and periostin in peripheral venous blood." (PMID 28429138, 2017). "In addition, among NF-κB-mediated cytokines, the secretion levels of IL-4, TNF-α, and eotaxin were significantly decreased by Rg3 in asthma tissues." (PMID 28116321, 2016). "Pro-inflammatory cytokines, such as TNF-α, IL-1β, and IL-6, are involved in both asthma and COPD and may play a role in amplifying inflammation and thus determining disease severity." (PMID 27812337, 2016). "Clinical trials of agents targeting TNF-α have been shown to be effective in asthma management." (PMID 26783416, 2016). "In addition to Th2-types cytokines, Th1 cytokines, such as TNF-α, have also been shown to play an important role in the pathogenesis of asthma." (PMID 27617014, 2016).
asthma (continued). "Our findings with VVHE suggest that the V. vinifera fruits could act in asthma via its neutralizing effects on TH2 derived pro-inflammatory (TNF and IL-1β) and inflammatory (IL-4 and IL-5) cytokines, key elements in the pathophysiology of bronchial asthma." (PMID 27536321, 2016). "Accumulating data have shown that TNF-α is markedly increased during the process of asthma." (PMID 26783416, 2016). "Some studies have shown that traditional acupuncture is able to interfere with the regulation of both systemic (e.g., interleukin (IL)-10, IL-4) and pro-inflammatory markers (IL-6, IL-1β, tumor necrosis factor alpha (TNF-α)) in some diseases such as asthma and rhinitis." (PMID 27590454, 2016). "Mice knock-out for Dok1 were hypersensitive to LPS showing high levels of TNFα and NO while triple KO mice (Dok1-2-3) showed spontaneous pulmonary inflammation, with hallmarks of asthma, including eosinophilia, goblet cell hyperplasia, and subepithelial fibrosis." (PMID 27169516, 2016). "Initial studies in severe asthma using hMabs which bind TNFα showed promise; however, an increase in infections and malignancies during treatment with one anti-TNF hMab, Golimumab, when compared with placebo has halted further studies in asthma of this class of anti-Th1 targeted therapies." (PMID 27942351, 2016). "The interest on TNF-α has developed in the last few years as a result of studies that showed an increase of this cytokine in bronchoalveolar lavage fluid of patients with severe asthma." (PMID 25671117, 2015). "The outcome of previous attempts to use various TNFα blocking agents in asthma has been meagre." (PMID 26494305, 2015). "Therefore, the trial was interrupted and it appears to be currently very unlikely that anti-TNF-α antibodies will be soon further evaluated for treatment of severe asthma." (PMID 25878402, 2015). "It is estimated that 20% of the total effect of 5OH-MEHP on asthma is mediated by TNFα 5′CGI." (PMID 25960783, 2015). "We believe that better understanding of the mechanism of TNFα methylation after environmental exposures may shed new light on improved therapeutic strategies for asthma." (PMID 25960783, 2015). "Previous data shows the anti-TNF therapy as a potential new strategy in severe refractory asthma." (PMID 26644796, 2015). "Does TNFα 5′CGI methylation link phthalate exposure with asthma?" (PMID 25960783, 2015). "Most of these drug evolutions have been dealing with asthma from a more general perspective, and it could be that the role of TNFα is of specific importance only during the circumstances reflected in the present set up." (PMID 26494305, 2015). "Moreover, 5-HTP suppresses the production of tumor necrosis factor-α (TNFα) in lipopolysaccharide (LPS)-treated mice and improves allergic lung inflammation in a murine asthma model." (PMID 26669765, 2015). "We demonstrated anincrease in the release of the cytokines GM-CSF, TNF-α, and IL-8 in experimental asthma.This effect might result in enhanced acetylation and local DNA unwinding, which couldcause increased inflammatory gene expression." (PMID 25923460, 2015). "Therefore, the objectives of this study were to determine the effect of DMPF-1 upon the synthesis of asthma-related proinflammatory chemokines in TNF-α-induced pulmonary epithelial cells and OVA-challenged BALB/c mice." (PMID 26300589, 2015). "The relevance of TNFα antagonists in decreasing eosinophil and/or basophil counts in vivo is unclear; however, anti-TNFα agents have been reported to decrease sputum histamine levels and improve asthma outcomes, airway hyper-responsiveness, and exacerbation rates." (PMID 25400924, 2014). "IL-2, IL-4, IL-6, IL-17a and TNF-α were reported to be involved in asthma." (PMID 24735374, 2014). "The levels of TNF-α elevated significantly after ovalbumin-induced asthma." (PMID 24660015, 2014). "Patients with genotypes related to higher TNFα production had increased frequency of asthma." (PMID 24603877, 2014).
asthma (continued). "A recent case series suggesting that anti-TNF may improve the condition of severe steroid-dependent refractory asthma, with frequent exacerbations and daily symptoms despite close repeated medical evaluation and maximal treatment including oral steroids." (PMID 25371053, 2014). "Despite the fact that more than ten GWAS of asthma have been reported, there is still no direct evidence proved the association with the TNF-α region." (PMID 24936650, 2014). "Furthermore, asthma inflammation is also induced by cytokines released from TNF-α, which can increase the production of more inflammatory mediators, including IL-8, granulocyte-macrophage colony-stimulating factor (GM-CSF), and other cytokines." (PMID 25101137, 2014). "TNF-α blockers are now regarded as potential novel medications in asthma and COPD management." (PMID 24587316, 2014). "The studies suggest that anti-TNF-α agents might improve the condition of a subgroup of patients severe steroid-dependent asthma, who have life-threatening exacerbations and complications of long-term steroid therapy." (PMID 24032029, 2013). "Thus, both the presence of M1 skewing factors (IFNγ, TNFα, or LPS) and the proinflammatory mediators released by M1 macrophages can contribute to asthma." (PMID 23533311, 2013). "Finally, a clinically-proven anti-IgE monoclonal antibody Omalizumab abrogated the IgE-induced mediators of asthma relevance such as IL-4, IL-6, IL-8, and TNF." (PMID 24499258, 2013). "Since pDCs exposed to NP switched their cytokine pattern from type I IFNs and IL-10 to TNF-α, it suggested that NP exposure might enhance the allergic responses of diseases such as asthma." (PMID 24039973, 2013). "The regulatory effects of IL-1β and TNF-α on ASM cell proliferation could have important consequences for development of asthma therapeutics." (PMID 23388501, 2013). "In murine models of allergen-dependent asthma, the proinflammatory cytokine TNF-α, produced by Th1 lymphocytes, macrophages and mast cells, induced airway recruitment of neutrophils and eosinophils via upregulation of epithelial and endothelial adhesion molecules." (PMID 23853765, 2013). "Therefore, the trial was interrupted and it appears to be currently very unlikely that anti-TNF-α antibodies will be soon further evaluated the for treatment of severe asthma." (PMID 23853765, 2013). "Some studies mentioned a relationship between TNF-α and severity of asthma." (PMID 24032029, 2013). "Therefore, several drugs targeting TNF-α have been evaluated for asthma treatment, including anti-TNF-α blocking antibodies such as infliximab and golimumab, as well as the soluble TNF-α receptor fusion protein etanercept." (PMID 23853765, 2013). "In conclusion, we have identified multiple SNPs and haplotypes in LTA4H, TNFα and IL4-Rα genes that constitute risk factors for the development of difficult asthma in children and demonstrate combined effects which confer greater risk than that obtained for any SNP individually." (PMID 23573270, 2013). "In this study, we investigated whether alveolar macrophages are stimulated by GCE through PAR-2 and whether production of TNF-α by alveolar macrophages plays a key role in the development of GCE-induced allergic inflammation in a mouse asthma model." (PMID 23094102, 2012). "Overall it appears that TNF-α inhibitors are effective in a sub-group of patients with asthma, and again identification of the correct patient population may improve clinical outcomes." (PMID 23189057, 2012). "Indeed, anti-TNF treatment has been reported to be beneficial in a subset of patients with severe asthma." (PMID 23043798, 2012). "Strategies aimed at the IL-5 dependent eosinophil recruitment into the airways or TNF-dependent airway hyperresponsiveness may hasten the resolution of asthma symptoms." (PMID 23043798, 2012). "The TNF-α is also involved in the initiation of allergic airway responses in asthma." (PMID 22726248, 2012).
asthma (continued). "In depth analyses of the asthma associated genes encoding for lymphotoxin alpha (LTA) and tumor necrosis factor (TNF) on chromosome 6p21.3, showed that differentially methylated CpG sites are enriched in the promoter region (5′UTR, 1st exon) and differ according to lymphoid versus myeloid lineages." (PMID 22848472, 2012). "However, the unfavorable risk/benefit ratio exhibited by golimumab does cast doubt on the future of anti-TNF therapy in severe asthma." (PMID 23189057, 2012). "TNF-α blockade also prevented the development of such asthma-like lesions." (PMID 23094102, 2012). "In patients with asthma, increased TNFα levels have been detected in the airways, and there is some evidence that increased airway TNFα may play a role in refractory asthma." (PMID 22954301, 2012). "Th1 cells, IFN-γ and TNF-α are considered important in severe asthma." (PMID 21205293, 2011). "Furthermore, we examined the expression of Th1 (IFN-γ) cytokines, Th2 (IL-4) cytokines and TNF-α, which are all important in asthma and are possible regulators of tenascin-C expression." (PMID 21205293, 2011). "The TNF-α protein plays a central role in inflammation and involves in pathogenesis of asthma." (PMID 20868478, 2010). "To test our hypothesis we measured serum concentrations of eleven cytokines and chemokines that were recently described to play an important role in asthma pathogenesis: IL-4, IL-5, IL-8, IL-10, IL-12 (p40), IL-13, IL-17, TNFα, GM-CSF, eotaxin, and IFNγ." (PMID 21179211, 2010). "However, in a study with the aim to examine levels of inflammatory markers in COPD and asthma patients, the influence of smoking on TNF-α serum concentration was identified only in the subgroup of COPD patients." (PMID 20534161, 2010). "In addition to its relevance to asthma in general, TNF-α mediates recruitment of neutrophils and eosinophils during airway inflammation." (PMID 20667094, 2010). "ADAM33, FcεRIβ, RANTES, TNF-α, ACE, β2-AR, IL-4R and IL-13 genes could be proposed as asthma susceptible genes in Chinese population." (PMID 20868478, 2010). "This study suggests that patients with refractory asthma may have up-regulation of the TNF-alpha axis and may benefit from treatment with a TNF-alpha blocking agent." (PMID 20016776, 2009). "TNF-α is a proinflammatory cytokine with pro-fibrotic features which has a key role in lower respiratory tract infections as well as in chronic inflammatory lung disease like asthma, bronchiolitis obliterans, or COPD." (PMID 19788749, 2009). "Other biologic agents targeting IL-5, and IL-4/IL-13 did not demonstrate any serious or severe treatment-related adverse events in asthma patients, There has been some conflicting information on the safety of TNF-alpha blocking agents in the treatment of asthma." (PMID 20016776, 2009). "Particularly, the protective effect of TNF GG genotype (alternatively, the risk effect of TNF GA/AA) seem to be related to asthma risk predominantly in subjects from nonsmoking families or children in low-ozone-exposure communities." (PMID 18709160, 2008). "Of note, the chromosome 6p region, containing the TNF gene, was more strongly linked to asthma among subjects who did not live with a smoker during infancy compared with those who lived with smokers." (PMID 17450233, 2007). "Because of the consistent association between parental smoking and childhood asthma and the involvement of TNF in cigarette smoke–induced inflammation responses, we examined the association of each LTA and TNF SNP with asthma stratified by exposure to a smoking parent in the home." (PMID 17450233, 2007). "Among cases with smoking parents in the home, none of the six LTA and TNF polymorphisms were associated with asthma." (PMID 17450233, 2007). "Our goal was to investigate whether genetic variation in TNF and LTA is associated with asthma and atopy and whether the association is modified by parental smoking in a Mexican population with high ozone exposure." (PMID 17450233, 2007).
asthma (continued). "Few studies have examined whether exposure to parental smoking modifies the relationship between TNF and LTA polymorphisms and asthma risk." (PMID 17450233, 2007). "The TNF-238A allele and the haplotypes containing the TNF-308A allele or the TNF-238A allele were associated with an increased childhood asthma risk predominantly in children with nonsmoking parents." (PMID 17450233, 2007). "We also found an association between the TNF-238A allele and asthma risk among children with nonsmoking parents in the home." (PMID 17450233, 2007). "In the present study, we found that TNF polymorphisms and haplotypes were associated with childhood asthma susceptibility predominantly among children who did not live with smoking parents." (PMID 17450233, 2007). "A recent study showed that the TNF-308 polymorphism modified the effect of home exposure to smokers on respiratory illness-related school absence among children mostly without asthma." (PMID 17450233, 2007). "In summary, we found that TNF polymorphisms and haplotypes were associated with childhood asthma susceptibility, especially among children without smoking parents." (PMID 17450233, 2007). "Finally, the data presented emphasize IL-13 and TNF-α as potential therapeutic targets for treating RSV induced-asthma." (PMID 16893457, 2006). "Taken together, these data suggest that cytokines other than TNFα may also have important roles in controlling asthma symptoms." (PMID 17034639, 2006). "Ten hub genes (including TNF, IL5, IL13, TLR4) were linked to 339 potential therapeutic agents; the exploratory network analysis highlighted overlap between predicted miRNA-regulated hub genes and existing asthma-relevant drug targets, including approved biologics." (PMID 42042546, 2026). "At the same time, among patients with controlled asthma, the coefficients of determination (R2) were 0.194, 0.093 and 0.152 for TNFα, IL-6 and IL-8, showing a weak dependence (r = 0.39 and r = 0.3050 for IL-6 and IL-8) and a moderate dependence (r = 0.44) for TNFα." (PMID 40361972, 2025). "Our data suggest that interventions designed to modulate epithelial responses to Th17 signals, limit viral replication, or dampen synergistic cytokine amplification (e.g., TNF-α or IL-1β blockade) may hold promise for reducing exacerbation severity in non-T2 asthma." (PMID 41332562, 2025). "The potential role of TNF‐α in asthma is related to its chemotactic properties in inflammatory cells and stimulation of the proliferation of muscle cells or fibroblasts, which may be important in processes related to remodeling in asthma." (PMID 41179970, 2025). "However, studies in asthma and other inflammatory diseases suggest that genetic variations in cytokines such as IL-5, IL-4, IL-13, and TNF may influence responses to biologic therapies." (PMID 40149465, 2025). "However, there is a notable absence of prospective studies evaluating the efficacy of TNF-α blockade in the treatment of ANCA-negative EGPA which is closely linked to asthma, with the majority of EGPA patients having a history of this condition." (PMID 40703351, 2025). "In the type 2-low asthma model, Sema3E-deficient mice exhibited increased tissue resistance and elastance, accompanied by elevated levels of neutrophils, dendritic cells, CD4 + T cells, and pro-inflammatory cytokines such as IL-17, TNF, IL-1β, CXCL-8, and MCP-1/CCL2." (PMID 40512736, 2025). "Asthma and AS may share inflammatory mediators and pathways, such as TNF-α and IL-17." (PMID 40661126, 2025). "Notably, an increase of immune cells was observed in the lungs of asthma mice, which may contribute to the elevated levels of TNF-α and IL-6 in the lung tissue." (PMID 39484217, 2024). "Injections of TNF-α into the airways of normal volunteers lead to increased bronchial reactivity, and prospective studies have shown that increased maternal weight leads to increased concentrations of TNF-α in the blood of infants, thereby enhancing the risk of asthma in infants." (PMID 39175819, 2024).